NRAS (NRAS proto-oncogene, GTPase)
Diseases named in the same sentence as NRAS in open-access papers (continued):
Sharing a sentence is not in itself a finding about the gene and the disease.
melanoma (continued). "Interestingly, our lab recently showed that NRAS/BRAF-driven melanoma, pancreatic, or colorectal cancer cell lines increase a metabolic process, called autophagy, upon MEK1/2 inhibition, a process we will discuss in the following section." (PMID 34298710, 2021). "In addition to NRAS mutations, several receptor tyrosine kinases (RTKs) such as c-KIT, EGFR, MET, and VEGFR have been reported to be involved in melanoma progression, invasion, or resistance to therapies, mainly targeting the MAPK pathway." (PMID 33918490, 2021). "TKB1 thus appears to be a promising target in NRAS-mutant melanomas." (PMID 34063141, 2021). "Mutations in BRAF, NRAS, NF1, and KIT have been all implicated as melanoma drivers." (PMID 33619278, 2021). "In a univariate analysis incorporating all factors, the ECOG performance score (P=0.004), LDH level (P<0.001), and NRAS mutation status (P=0.015) were significantly associated with PFS in noncutaneous melanoma." (PMID 34290710, 2021). "Therefore, we first determined the sensitivity of a panel of four NRAS mutant melanoma cell lines to inhibition of cell viability by trametinib treatment." (PMID 33921974, 2021). "In multivariate analyses NRAS mutation remains a predictor of worse survival independent of stage in mucosal melanomas." (PMID 34571863, 2021). "G9 also blocked colony growth in NRAS-mutant melanoma cells." (PMID 33613844, 2021). "MEKi are currently used for NRAS-mutant melanoma, but have shown modest efficacy as single agents." (PMID 35187538, 2021). "Downstream NRAS inhibition combination therapy may prove to be an effective therapy for patients suffering from melanoma." (PMID 33807778, 2021). "Given the potential for NRAS/BRAF/PI3K mutant melanoma to be particularly sensitive to RGS, it is important to evaluate whether RGS is effective in preclinical models for the treatment of melanoma." (PMID 34092233, 2021). "BRAF mutant melanoma cells, when compared to NRAS mutant ones, showed higher expression of Sema6A." (PMID 33858502, 2021). "Additionally, pharmacologic inhibition of the Rho/MRTF pathway by the small-molecule CCG-203971 significantly reduced in vitro cellular migration and invasion, as well as in vivo lung metastasis in the RhoC-expressing NRAS mutant melanoma cell line SK-Mel-147." (PMID 33921974, 2021). "We observed that gynecologic melanoma harbored distinct mutation rates in c-KIT, BRAF, SF3B1, KRAS and NRAS genes compared with non-gynecologic melanoma." (PMID 34102999, 2021). "Complementary studies on other NRAS mutant melanoma cell lines are required to show that such high TRT radiosensitivity is related to NRAS mutation, although previous EBRT studies have reported increased radiosensitivity in vitro and in vivo when NRAS is mutated." (PMID 33804655, 2021). "Notably AXL upregulation is associated with MITFlow state in NRAS- and BRAF-mutated melanomas leading to increased survival, therapy resistance and dormancy." (PMID 33870460, 2021). "Although a direct mechanism involving BRAFV600E in the epigenetic silencing of RASSF1A has never been reported, RASSF1A hypermethylation has been found alongside BRAF (and NRAS) mutations, suggesting a synergistic effect of MAPK pathway mutations and the loss of RASSF1A on melanoma growth." (PMID 34066022, 2021). "Finally, THRB is one of the thyroid hormone receptors, and defects in its gene are known to confer generalized thyroid hormone resistance, thus opening up new perspectives for the putative use of thyroid hormone therapy to treat NRAS-mutant melanomas." (PMID 34944843, 2021). "Somatic mutations in genes encoding protein actors of this phosphorylation cascade constitutively activate the MAPK pathway: mutations in BRAF, neurofibromin 1 (NF1), NRAS, and c-KIT are the most frequent, representing 50, 20, 20, and 2% of melanomas, respectively." (PMID 33804655, 2021).
melanoma (continued). "A number of studies have reported the role of Erk5 in the lack of efficacy of MAPK inhibitors in melanomas harboring NRAS and B-Raf mutations." (PMID 34946644, 2021). "In the noncutaneous melanoma population, 12 from 114 patients had NRAS mutations, including 9 acral and 3 mucosal melanoma patients." (PMID 34290710, 2021). "We did not observe a correlation between MITF expression and the most common BRAF, NRAS, and NF1 mutations found in melanoma, indicating that the gene expression changes observed are controlled via transcriptional regulation, directly or indirectly imposed by MITF." (PMID 33438577, 2021). "In this study, we demonstrate that the combination of a Rho/MRTF pathway inhibitor, CCG-222740, and the MEK inhibitor trametinib synergistically inhibits the viability of a subset of NRAS mutant melanoma cells and induced apoptosis in melanoma lines with a highly activated Rho/MRTF pathway." (PMID 33921974, 2021). "In 1/6 of patients with neurocutaneous melanosis (NCM) NRAS p.Gln61Lys variant was detected, whereas no variants were identified in the two cases diagnosed with melanoma." (PMID 34643354, 2021). "Furthermore, we performed XAF1 knockdown in additional BRAF and NRAS mutant melanoma cultures (Figure [Link], [Link]) and observed the same trend." (PMID 33734579, 2021). "Thus, pharmacological targeting of the translation initiation complex component eIF4A, combined with an MEK inhibitor, seems to be an efficient treatment for NRAS-mutant melanomas." (PMID 34063141, 2021). "Therefore, efforts to develop targeted therapies for NRAS mutant melanomas have focused on signaling components downstream of NRAS in the MAPK pathway, such as mitogen-activated protein kinase kinase (MEK)." (PMID 33921974, 2021). "Especially for NRAS, mutant melanoma combination therapy is essential." (PMID 33921303, 2021). "Polymerase Chain Reaction (PCR) and Sanger sequencing techniques were performed to identify the mutational status of BRAF, NRAS, KRAS, NF1, KIT, PDGFRA and SF3B1 on 19 melanomas of the female genital tract, paired with 25 cutaneous melanomas, 18 acral melanomas and 11 melanomas of nasal cavity." (PMID 34102999, 2021). "A total of 206 advanced melanoma patients were enrolled in this study, including 92 cutaneous melanoma patients with 12 NRAS mutations and 114 noncutaneous melanoma patients with 21 NRAS mutations." (PMID 34290710, 2021). "Finally, MEK inhibitors have also been studied in combination with ROCK inhibitors (GSK269962A) in vitro and in vivo, showing the suppression of the growth of NRAS mutant melanomas." (PMID 34831002, 2021). "The sensitivity of mutated NRAS MM cells to MEK inhibitor treatment is described increasingly often in the literature, indicating that NRAS gain could be a new therapeutic target for melanoma." (PMID 34638245, 2021). "In addition, by generating belvarafenib-resistant NRAS-mutant melanoma cells and analyzing circulating tumor DNA from patients treated with belvarafenib, new recurrent mutations in ARAF have been identified to confer the treatment resistance." (PMID 34924562, 2021). "A key difference in the melanoma mutational profiles between Asians and Caucasians is that in Caucasians, most melanomas, which are predominantly cutaneous melanomas, are driven by UV-induced point mutations, including driver mutations in BRAF and NRAS." (PMID 34149718, 2021). "Overall, these results suggest that MAPKinase activation may co-occur with AhR-dependency and that elevated AhR levels may serve as a biomarker of sensitivity to MEK inhibitors in the context of NRAS-mutant melanoma." (PMID 33451095, 2021). "While RAS has been the first oncogene described for melanoma, no successful NRAS mutated protein inhibitor has gained clinical approval." (PMID 34885944, 2021).
melanoma (continued). "For an unbiased global transcriptional comparison, we conducted RNA-seq on human melanoma NRAS-driven cell line SKMEL2 iSATB2, since it had the strongest invadopodia phenotype, and identified transcriptional differences induced by SATB2 overexpression (with/without Dox induction for 48 hr)." (PMID 33527896, 2021). "As such, combinations therapies have been sought for NRAS-mutant melanoma." (PMID 35187538, 2021). "Since 80% of human cutaneous melanomas harbor activating hot-spot mutations in either BRAF or NRAS (e.g., BRAFV600, NRASG12, or NRASQ61), we examined the nf1/pten-mutant zebrafish melanomas for spontaneous mutations at equivalent sites in the zebrafish orthologues." (PMID 34331013, 2021). "Next, a QBDA melanoma panel was applied to 16 FFPE and 7 FF clinical tissue samples, and we found co-existence of BRAF V600E and low-frequency NRAS Q61K mutations in one FFPE tissue." (PMID 34675197, 2021). "Novel therapies targeting autophagy, which may promote cancer cell death in chemotherapy-resistant melanomas, are of great interest, especially for BRAF/NRAS wild-type melanomas." (PMID 34068618, 2021). "However, for NRAS mutant melanoma, MEK inhibitors and other targeted therapies are still under investigation." (PMID 34290710, 2021). "Indeed, CCG-222740 was found to potentiate trametinib action in the subset of NRAS mutant melanoma cell lines that showed high activation of the Rho/MRTF pathway." (PMID 33921974, 2021). "The most prevalent significantly mutated genes in melanoma such as BRAF, NRAS, KRAS, HRAS, and NF1 were also explored; the results indicated that the high-FRGs score group have lower mutation frequencies in NRAS, KRAS, and NF1 compared to the low-FRGs score group." (PMID 34745259, 2021). "Additionally, NRAS mutations and CCDN1 amplifications, which are particularly common among Chinese patients with melanoma, were associated with poor response to toripalimab treatment (ORRs of 6.3% and 0%, respectively)." (PMID 34149718, 2021). "A total of 206 patients were assessed, including 92 cutaneous melanoma patients with 12 NRAS mutations and 114 noncutaneous melanoma patients with 21 NRAS mutations." (PMID 34290710, 2021). "Mutations in the TERTprom lead to a 2-fold to 4-fold increase in the transcription of TERT, along with enhanced telomerase activity, and are often found in BRAFV600 and NRAS-mutant melanomas, where the combined alterations cooperate in boosting cancer progression and aggressiveness." (PMID 34123788, 2021). "Low-CSD melanomas have a moderate mutational burden and are associated with BRAFV600E mutations while high-CSD melanomas have a higher mutational burden and are associated with NRAS, NF1, and BRAFnonV600E mutations." (PMID 35008286, 2021). "Approximately 20% of melanoma patient tumors harbor mutations in the neuroblastoma RAS viral oncogene homolog (NRAS), 60% have a mutually exclusive mutation to NRAS in the v-raf murine sarcoma viral oncogene homolog B1 (BRAF), and 31% have mutation in the phosphoinositide 3-kinase (PI3K) pathway." (PMID 34092233, 2021). "We next sought to determine whether the combination of MEK and HSP70 inhibition was efficacious in the treatment of NRAS-mutant melanoma." (PMID 35187538, 2021). "Crucial pathway alterations contribute to bioenergetic profile dysregulation in human melanoma, including B-Raf proto-oncogene serine/threonine-protein kinase (BRAF) mutations, neuroblastoma RAS viral oncogene protein (NRAS) overexpression, or deletion of PTEN, among others." (PMID 34895222, 2021). "The development and progression of superficial spreading melanoma, which is common in Caucasoid patients, is correlated with UV exposure, which can cause genetic mutations, such as BRAF and NRAS mutations, which lead to the development and progression of malignant melanoma." (PMID 34207144, 2021). "BRAF, NRAS and c-KIT mutations in melanoma have shown to be distinct clinic-pathological entities." (PMID 34572865, 2021).
melanoma (continued). "Therefore, it is critical to elucidate the mechanisms of resistance of NRAS mutant melanomas to MEK inhibitors and to develop new treatment strategies to overcome these clinical challenges." (PMID 33921974, 2021). "In this work, we explored the use of MEK inhibitors for NRAS-mutant melanoma." (PMID 35187538, 2021). "S6K1 inhibition may resensitize NRAS-mutant melanoma carrying PIK3CA E545K to combined MEK and CDK4/6 inhibition." (PMID 34804979, 2021). "On the other, chronic sun exposure often leads to melanoma harboring NRAS mutation, without any involvement of nevi proneness." (PMID 34924562, 2021). "In addition to BRAF mutant melanoma, enhanced mTORC1 activity has also been reported to associate with acquired resistance to combined inhibition of CDK4/6 and MEK in NRAS-mutant melanomas." (PMID 34304249, 2021). "These melanomas rarely harbor BRAF, NRAS, or NF1 mutations (triple wild-type)." (PMID 34571969, 2021). "Furthermore, combined inhibition of MEK plus autophagy showed synergistic antitumor activity against patient-derived xenografts of KRAS-mutant PDAC and NRAS-mutant melanoma." (PMID 34301278, 2021). "Immunotherapy is still the first-line recommendation for advanced NRAS mutant melanoma." (PMID 34290710, 2021). "Two slow-growing UM cell lines XMP46 and MM28 (GNAQ/11-mutation, BAP1-negative) were not sensitive to VP, and neither were the two conjunctival melanoma cell lines (BRAF/NRAS-mutation)." (PMID 33798262, 2021). "This novel combination is a promising therapeutic avenue for NRAS-mutant melanoma." (PMID 35187538, 2021). "In the context of DPN, NRAS mutations have been reported thus far in sporadic observations, including a combined nevus with a DPN component and a case of atypical DPN progressing to melanoma." (PMID 34205480, 2021). "The isobologram summarizes the combination index (CI) at the IC50 when the SMO inhibitor MRT-92 and the BRD4-degrader MZ1 were combined, showing a moderate synergistic anti-proliferative effect (CI < 1) in melanoma cells independently of their BRAF, NRAS, and NF1 mutational status." (PMID 33958721, 2021). "These drugs elicit partial responses in NRAS-mutant melanoma, and in some BRAF-mutant cancers." (PMID 33367512, 2021). "Furthermore, inhibitors of Rho/MRTF-regulated gene transcription, CCG-222740 and Rho-kinase inhibitor, markedly enhance the sensitivity of NRAS mutant melanoma cells to the MEK inhibitor trametinib." (PMID 33921974, 2021). "Targeting MEK is currently the most developed strategy in NRAS mutant melanomas." (PMID 34831002, 2021). "Furthermore, patients with activating mutations in NRAS have a poorer prognosis, are refractory to BRAF inhibition, and exhibit a greater incidence of brain metastases than patients with either BRAF-mutant or BRAF/NRAS wild-type melanoma." (PMID 35187538, 2021). "Furthermore, skin melanoma is characterized by frequent amplifications of BRAF (7q34), NRAS (1p13.2), KIT (4q11) oncogenes (major mutated genes in melanoma) but also by EGFR (7p11.2) and MET (7q31.2) genes." (PMID 34885093, 2021). "Inhibitors to MEK have shown some promise for NRAS-mutant melanoma." (PMID 35187538, 2021). "In addition to melanoma-associated mutations such as BRAF, NRAS, PTEN and cell cycle regulators, the expansion of melanoma is affected by the extracellular matrix surrounding the tumor together with immune cells." (PMID 35127523, 2021).
melanoma (continued). "We next evaluated the concomitant BRN2 locus alterations, BRAF/NRAS mutations, and CDKN2A/PTEN alterations and found the most frequent genetic constellation that co-occurs with BRN2 loss in melanoma to be BRAFV600X mutation together with mono-allelic PTEN loss." (PMID 34140478, 2021). "About half of the melanoma patients harbor activating mutation in oncogenes involved in the mitogen-activated protein kinase (MAPK) pathway, e.g., BRAF or NRAS and/or constitutive activation of the cell cycle modulating phosphoinositide 3-kinase (PI3K) signaling pathway." (PMID 33578810, 2021). "Indeed, early clinical trials of dual MEK and CDK4/6 inhibition in NRAS mutant melanoma demonstrated encouraging results (NCT01719380)." (PMID 34025662, 2021). "In a recent study of MAPK pathway alteration in cutaneous and unknown primary melanomas, time to treatment failure (TTF) was shorter for patients with NRAS Q61 mutations." (PMID 34290710, 2021). "Efficacy of immunotherapy in NRAS mutant and NRAS wild-type melanoma." (PMID 34290710, 2021). "Combination of MEK and PI3K/mTOR1,2 inhibition could induce apoptosis in NRAS mutant melanoma cancer cells and shrink tumor in mouse xenograft model." (PMID 34301278, 2021). "In addition, a significant difference in the increased PLA1A positive cells was found between advanced BRAF/NRAS-MUT melanoma stages and naïve/control melanoma samples." (PMID 33723350, 2021). "Typically, 15–20% of malignant melanomas have mutations in the neuroblastoma RAS viral oncogene homolog (NRAS) gene, but no cases of NRAS-mutated primary malignant melanoma of the lung have been reported in the English literature." (PMID 32028967, 2020). "We here report on a novel mechanism of drug resistance in NRAS‐mutant melanoma." (PMID 31549767, 2020). "Similarly, the level of NRAS, a known melanoma marker, was reduced by tenfold in a melanoma patient, but the patient’s disease nevertheless progressed and so did the CCF value of the patient." (PMID 32738923, 2020). "Furthermore, SHP-2 acts as an oncogene in BRAF wild-type (either NRAS mutant or wild-type) melanoma cells." (PMID 33003469, 2020). "In line with the other results, Melanoma-associated mutations (BRAF, NRAS, c‐Kit) were absent and malignant melanoma was ruled out." (PMID 31309284, 2020). "Importantly, this combination also is effective in mutant NRAS driven melanomas, which are insensitive to MEK or RAF inhibitors." (PMID 32046099, 2020). "These represent potential target pathways for NRAS‐mutant melanoma." (PMID 33073517, 2020). "Conversely, resistance to MEK inhibition in NRAS-mutant melanoma may be mediated through activation of the anti-apoptotic cAMP/MITF/Bcl-2 pathway." (PMID 32517051, 2020). "Therefore, MAPK pathway inhibitors, such as MEK inhibitors (MEKi), are the typical therapeutic approach when it comes to NRAS‐mutant melanoma (Munoz‐Couselo, Adelantado, Ortiz, Garcia, & Perez‐Garcia, 2017; Santarpia, Lippman, & El‐Naggar, 2012)." (PMID 31549767, 2020). "It exhibits antitumor activity against BRAFV600E mutant and NRAS mutant melanoma." (PMID 32092958, 2020). "MEKi has proven to be effective also in NRAS-mutant melanomas." (PMID 32054078, 2020). "XL888 inhibited cell proliferation also in melanoma cells with intrinsic and acquired resistance to BRAF inhibitors that were dependent on different mechanisms including either overexpression of cyclin D1, PDGFR-β or COT, or NRAS mutation." (PMID 31659567, 2020).